CLN3 (CLN3 lysosomal/endosomal transmembrane protein, battenin)
Diseases named in the same sentence as CLN3 in open-access papers (continued):
Sharing a sentence is not in itself a finding about the gene and the disease.
Batten disease (continued). "For example, pathogenic changes in CLN3 (MIM *607042) are well known as causative of the severe disease juvenile neuronal ceroid lipofuscinosis or Batten disease, a rare neurodegenerative disorder associating early retinal degeneration and progressive neurologic deterioration." (PMID 31736247, 2020). "CLN3 mutations cause the fatal neurodegenerative disorder, CLN3 Batten disease." (PMID 31628420, 2019). "The most common, juvenile onset form of Batten disease, CLN3 disease, is caused by mutations in CLN33, which encodes a lysosomal/endosomal transmembrane protein of unknown function." (PMID 31628420, 2019). "Recent studies show that CLN3 mutations may also result in a nonsyndromic retinal degeneration whose onset differs considerably from classical Batten disease." (PMID 31568712, 2019). "Interestingly, mapping the mutations causative of Batten Disease on a CLN3 topological model reveals that most of these mutations face the luminal side of the intracellular compartments." (PMID 31568712, 2019). "The most common form of NCL is Batten disease, caused by mutations in the membrane protein, CLN3." (PMID 29233882, 2017). "Defective autophagosome maturation associated with increased autophagic and lysosomal compartments was observed in the Cln3-deficient mouse that models Batten disease, and also in patient fibroblasts as well as patient-specific induced pluripotent stem cell (iPSC)-derived neuronal cells." (PMID 29233882, 2017). "The most common form, juvenile CLN3 (Batten) disease is caused by mutations in the CLN3 gene." (PMID 29089465, 2017). "Juvenile neuronal ceroid lipofuscinosis (JNCL or Batten disease) is the most prevalent inherited neurodegenerative disease in childhood caused by autosomal recessive loss-of-function mutations in the CLN3 gene." (PMID 29135436, 2017). "However, the mechanisms underlying how CLN3 loss develops Batten disease remain largely unclear." (PMID 39917569, 2025). "Indeed, a recent study showed that the protein encoded by CLN3, a gene mutated in Batten disease, might be responsible for transport of these glycerophosphodiesters from lysosomes." (PMID 38451736, 2024). "Juvenile neuronal ceroid lipofuscinosis (JNCL or Batten disease) caused by mutations in the CLN3 gene is the most prevalent inherited neurodegenerative disease in childhood resulting in widespread central nervous system dysfunction and premature death." (PMID 29135436, 2017). "Juvenile Neuronal Ceroid Lipofuscinosis (JNCL), or Juvenile Batten Disease, is an autosomal recessively inherited lysosomal storage disorder caused by mutations in the CLN3 gene." (PMID 24736558, 2014). "The Cln3 gene, prioritised in our analysis for CD risk in ILC3s but not in CD4+ T cells, underlies the majority of cases of the neurodevelopmental disorder Batten disease." (PMID 41573945, 2026). "While immune features have been reported in Batten disease and other lysosomal disorders, the function of Cln3 in the immune system remains poorly understood." (PMID 41573945, 2026). "Here, we apply a similar ASO approach for treating retinal dysfunction in a pig model of CLN3 Batten disease, which is more representative of human vision." (PMID 41189054, 2025). "CLN3 mutation causes Juvenile neuronal ceroid lipofuscinosis (JNCL, also known as Batten disease), an early onset neurodegenerative disorder." (PMID 39917569, 2025). "Our findings demonstrate the utility of an ASO-based approach to treat retinal dysfunction in CLN3 Batten disease and support broader ASO applications for treating ocular diseases." (PMID 41189054, 2025). "This study presents the first evidence of age-related and sex-specific central auditory processing abnormalities in the Cln3-/- mouse model of Batten disease." (PMID 41199165, 2025). "CLN2 (OMIM 204500) and CLN3 (OMIM 204200) diseases are the most common types of Batten disease, also known as neuronal ceroid lipofuscinoses (NCLs)." (PMID 39821609, 2025).
Batten disease (continued). "Taken together, our results demonstrate the potential of ASOs as a therapeutic for treating the eye in CLN3 Batten disease." (PMID 41189054, 2025). "CLN2 and CLN3 diseases, the most common types of Batten disease (also known as neuronal ceroid lipofuscinosis), are childhood dementias associated with progressive loss of speech, language and feeding skills." (PMID 39821609, 2025). "While the family impact of CLN3 and other forms of Batten disease is immense, many aspects of the parental and family experience remain elusive." (PMID 38500130, 2024). "This work adds new insights to the body of evidence documenting family and parental experiences with CLN3 Batten disease while also highlighting the vast unmet need that remains." (PMID 38500130, 2024). "Our stable cln3 mutant zebrafish lines represent therefore a novel tool to make rapid progress in elucidating the physiological function of CLN3 and potentially screen for molecules that can rescue CLN3 function and benefit Batten disease patients." (PMID 38195117, 2024). "Mouse models of CLN3 Batten disease, a rare lysosomal storage disorder with no cure, have improved our understanding of CLN3 biology and therapeutics through their ease of use and a consistent display of cellular pathology." (PMID 37305926, 2023). "CLN3 Batten disease (CLN3 disease, also known as juvenile NCL) is caused by mutations in the ceroid lipofuscinosis neuronal 3 gene (CLN3)." (PMID 37035740, 2023). "CLN3 disease was formerly known as ‘juvenile neuronal ceroid lipofuscinosis’ (JNCL) and can initially present as with isolated visual symptoms or with progressive neurological dysfunction." (PMID 36964447, 2023). "Given these advantages, our team developed a novel porcine model of CLN3 disease that replicates the histopathological, behavioral and visual abnormalities experienced by patients with CLN3 Batten disease." (PMID 37305926, 2023). "CLN3 is a lysosomal transmembrane protein and loss of CLN3 is known to cause a juvenile lethal neurodegenerative lysosomal storage disorder (LSD), called Batten disease." (PMID 39872513, 2023). "Although sex discrepancies have been observed in human subjects with CLN3-Batten disease, sparse information exists for other forms of NCLs." (PMID 36369162, 2022). "We have previously found using the Cln3−/− and Cln3Δex7/8 mouse models of juvenile Batten disease that Cln3−/− and Cln3Δex7/8 males have more and more severe neurological phenotypes than females and thus, are more suitable for therapeutic studies." (PMID 35637265, 2022). "CLN3 disease (also known as Batten disease or Neuronal Ceroid Lipofuscinosis (NCL) type 3) is a neurodegenerative disorder of childhood onset." (PMID 35627432, 2022). "In a human cerebral organoid model of CLN3-JNCL (juvenile neuronal ceroid lipofuscinosis), the disease characteristics, i.e., the increased presence of autophagic vacuoles, can be observed by TEM." (PMID 35324810, 2022). "One of the most prevalent NCL forms in Northern European countries is caused by mutations in the CLN3 gene (CLN3 disease, also called juvenile NCL or Batten disease)." (PMID 35699772, 2022). "iPSCs have successfully been differentiated into brain organoids that have been used as a model for CLN3 Batten disease." (PMID 33792748, 2021). "Because Batten disease is primarily a neurodegenerative disorder, an important issue is the function of CLN3 membrane protein in brain tissue." (PMID 33137890, 2020). "CLN3 Batten disease (CLN3 disease) is a pediatric lysosomal storage disorder that presents with progressive blindness, motor and cognitive decline, seizures, and premature death." (PMID 32601357, 2020). "In 2019, pigs were created that had a deletion in their CLN3 gene similar to that of patients with Batten disease (JNCL)." (PMID 33137890, 2020). "The most common name for the disease is Batten disease which was first used to describe the juvenile and presumably the CLN3 form (prior to the discovery of the gene)." (PMID 31568712, 2019).
Batten disease (continued). "Batten disease, or juvenile NCL, is a fatal neurodegenerative disorder that occurs due to mutations in the CLN3 gene." (PMID 31572287, 2019). "This possibly reflects the observation reported in CLN3-Batten disease patients females present with a faster disease progression." (PMID 30665444, 2019). "On average, female CLN3-Batten disease patients present with symptoms 1 year later than their male counterparts, have accelerated disease progression following symptom onset, and die 1 year earlier than males." (PMID 30665444, 2019). "In the Batten disease field, studies on CLN3-Batten disease, a genetically distinct subtype of Batten disease, have shown differences in disease progression in patients depending on sex." (PMID 30665444, 2019). "Juvenile NCL (JNCL, or CLN3 disease), is caused by mutations in the CLN3 gene, and is the most common of these disease subtypes." (PMID 31572287, 2019). "Accumulation of lysosomal storage material and activation of astrocytes and microglia are early neuropathological hallmarks of CLN3 Batten disease that are recapitulated in Cln3−/− mice." (PMID 31628420, 2019). "Thus, the mutations in CLN3 gene led to the conformational changes of those proteins may cause the subsequent deviations in signaling cascades, which is considered as a molecular mechanism of juvenile Batten disease." (PMID 30621751, 2018). "This mouse model also recapitulates many phenotypic similarities with human CLN3-Batten disease, including accumulation of autofluorescent storage material, neuronal degeneration, glial activation, and behavioral deficits." (PMID 30086172, 2018). "Our results suggest that colony variation in the Cln3Δex7/8 mouse model of CLN3-Batten disease can influence potential biomarkers of the disease." (PMID 30086172, 2018). "To expedite the identification of useful surrogate markers, we and others have turned to a mouse model of CLN3-Batten disease." (PMID 30086172, 2018). "The Cln3Δex7/8 mouse model of CLN3-Batten disease has become an invaluable tool for studying disease pathology, as it recapitulates many of the phenotypic characteristics associated with human CLN3-Batten disease." (PMID 30086172, 2018). "CLN3-Batten disease is a rare, autosomal recessive disorder involving seizures, visual, motor and cognitive decline, and premature death." (PMID 30086172, 2018). "Mutations in any one of 14 genes confer NCL, with variation at the CLN3 locus being the most common cause of juvenile NCL, also known as Batten disease." (PMID 28913343, 2017). "A further five individuals from four families returned a molecular diagnosis consistent with syndromic conditions (CLN3; Batten disease/AHI1; Joubert syndrome / IFT140; Mainzer‐Saldino syndrome) and were referred for clinical re‐evaluation." (PMID 29178642, 2017). "Treatment with autophagy inducers has also been found to be beneficial in other LSDs, including CLN3 disease (Batten disease)." (PMID 29233882, 2017). "If Cln3Δex7/8 is indeed a null mutation then the behavioral phenotypes and their progression in the Cln3−/− and Cln3Δex7/8-knock-in mouse models of juvenile Batten disease should be very similar." (PMID 26035843, 2015). "It has been reported that the deletion of btn1+, a homolog of the human Batten disease gene CLN3, results in enlarged and more alkaline vacuoles." (PMID 26083598, 2015). "The two most commonly utilized mouse models of juvenile Batten disease are Cln3-knockout (Cln3−/−) and Cln3Δex7/8-knock-in mice, the latter mimicking the most frequent disease-causing human mutation." (PMID 26035843, 2015). "Juvenile Batten disease (juvenile neuronal ceroid lipofuscinosis, JNCL) is a devastating neurodegenerative disease caused by mutations in CLN3, a protein of undefined function." (PMID 24792215, 2014). "Juvenile neuronal ceroid lipofuscinosis (JNCL), caused by mutations in CLN3, is a lysosomal storage disease (LSD) with an incidence reaching 1∶25,000 in northern European countries." (PMID 24792215, 2014).
Batten disease (continued). "btn1, the Schizosaccharomyces pombe orthologue of the human Batten disease gene CLN3, exerts multiple cellular effects." (PMID 18346214, 2008). "Restoring mitochondrial health could improve brain metabolism, inflammation control, neurotransmitter regulation, and neuronal survival, highlighting mitochondria as promising therapeutic targets in CLN3 Batten disease." (PMID 42129767, 2026). "We have shown previously that intracerebroventricular (ICV) delivery of an ASO that induces Cln3 exon 5 skipping during pre-mRNA splicing is therapeutic in a mouse model of CLN3 Batten disease, decreasing abnormal histopathology throughout the brain and improving sensorimotor coordination." (PMID 41189054, 2025). "Importantly, the identification of potential compensatory processes in male Cln3-/- mice in the current study introduces a novel avenue for therapeutic discovery aimed at preserving or restoring auditory function in Batten disease." (PMID 41199165, 2025). "Therefore, the direct mechanisms underlying how CLN3 regulates JAK/STAT signaling and subsequent phenotype of Batten disease should be investigated by other methods or in other organisms." (PMID 39917569, 2025). "In patients with CLN3 Batten disease, there is severe loss of the photoreceptor ONL layer in the macula and mid-periphery, along with the reduced ERG a-wave responses, suggesting that photoreceptor cells are profoundly affected by CLN3 disease." (PMID 41189054, 2025). "Exon-skipping SSOs have been explored for targeting other diseases, such as correcting the reading frame in CLN3 Batten’s disease (below), bypassing an inframe CEP290 exon 41 that carries pathogenic mutations for Jobert syndrome, and suppressing a cryptic splice site in CFTR cystic fibrosis." (PMID 39119251, 2024). "Finally, parents of children with neuronal ceroid lipofuscinosis 3 (CLN3) disease reported positive implications of the disease such as an increased sense of empathy and responsibility in the healthy sibling." (PMID 39103591, 2024). "CLN3 disease is thought to be the most common form of Batten disease (also known as neuronal ceroid lipofuscinosis), a family of rare lysosomal disorders with characteristic accumulation of autofluoresent ceroid lipofuscin in lysosomes and predominant central nervous system presentation." (PMID 38500130, 2024). "These works suggest a promising exon-skipping strategy for CLN3 (Δex78) Batten’s disease." (PMID 39119251, 2024). "Together, our findings reveal that CLN3 functions as a link between the M6P-dependent trafficking of lysosomal enzymes and lysosomal reformation pathway, explaining the global impairment of lysosomal function in Batten disease." (PMID 37400440, 2023). "As vision loss primarily due to retinal degeneration is a characteristic phenotype of patients with CLN3 Batten disease, we investigated whether CLN3Δex7/8 miniswine show retinal degeneration." (PMID 37305926, 2023). "In addition, efficacy with AAV9 has also been demonstrated in multiple Batten diseases, including CLN3, CLN6, and CLN8, using other routes of administration." (PMID 35025759, 2022). "CLN3 is mostly related to Batten disease or juvenile, neuronal ceroid lipofuscinosis (JNCL), but hypomorphic alleles are also associated with non-syndromic RP." (PMID 34828430, 2021). "Therefore, this novel model shows its utility as a pathological model of CLN3 Batten disease, and its potential as a tool for screening tailored genetic therapies in the future." (PMID 32601357, 2020). "In summary, our results in Cln3−/− mice suggest that acidified drinking water may have beneficial effects for CLN3 Batten disease patients." (PMID 31628420, 2019). "In summary, we sought to elucidate reproducible, non-invasive, surrogate biomarkers in the Cln3Δex7/8 mouse model of CLN3-Batten disease that could potentially be translated to human patients." (PMID 30086172, 2018).
Batten disease (continued). "The data obtained are interpreted and lead to the formulation of the hypothesis that deregulation of MAPK pathways may be involved in CLN3-dependent Batten disease." (PMID 30621751, 2018). "The most common NCL is juvenile CLN3 disease or juvenile Batten disease." (PMID 29780879, 2018). "In this study, we focus on CLN3-Batten disease, which has symptomatic onset between 5–10 years of age; it most often begins with progressive blindness and intractable seizures, followed by cognitive and motor deterioration, and ultimately premature death by the 20s-early 30s." (PMID 30086172, 2018). "In the current study, we cross-compared a number of biological parameters in blood from Cln3Δex7/8 mice and control, non-disease mice on the same genetic background from multiple animal facilities in an attempt to better define a surrogate marker of CLN3-Batten disease." (PMID 30086172, 2018). "Furthermore, he developed a model system for Batten disease, a neuropsychiatric disease of school-aged children using Cln3-/- mice." (PMID 22360825, 2012). "The current review focuses on classic juvenile NCL (JNCL) or the so-called Batten (Batten-Spielmeyer-Vogt; Spielmeyer-Sjogren) disease, which represents the most common and the most studied form of NCL, and is caused by mutations in the CLN3 gene located on human chromosome 16." (PMID 33137890, 2020). "The first is that acidified water may have therapeutic effects in CLN3 Batten disease." (PMID 31628420, 2019). "However, the role of CLN3 in the pathological mechanism leading up to Batten disease still remains unclear." (PMID 19440452, 2008). "BACKGROUND: CLN3 disease, also called Juvenile Neuronal Ceroid Lipofuscinosis (JNCL), or Batten disease, is an ultra‐rare, neurodegenerative lysosomal storage disorder generally affecting individuals during the first decade of life." (PMID 41808212, 2026). "We have systematically characterised speech, language and feeding in the two most common types of Batten disease, CLN2 and CLN3, identifying different speech and language profiles between the two conditions." (PMID 39821609, 2025). "Juvenile neuronal ceroid lipofuscinosis (JNCL, CLN3) is a childhood-onset neurodegenerative disease with prominent symptoms comprising a pediatric dementia syndrome with intellectual decline, loss of adaptive skills, and mood and behavioral impairments." (PMID 37113550, 2023). "Viral-delivered gene therapies have been explored preclinically for most forms of Batten disease, and clinically for CLN2, CLN3, CLN5, CLN6, and CLN7, with results pending (NCT#s: 01161576, 00151216, 01414985, 03770572, 04273243, 05228145, 04737460)." (PMID 37035740, 2023). "Juvenile neuronal ceroid lipofuscinosis (JNCL, CLN3) is a childhood-onset neurodegenerative disease with prominent symptoms comprising a pediatric dementia syndrome." (PMID 37113550, 2023). "In summary, we discovered that CLN3 plays a crucial role in the sorting of CI-M6PR and links this process with ALR, thus explaining the global lysosomal dysfunction observed in Batten disease." (PMID 37400440, 2023). "Ceroid lipofuscinosis type 3 (CLN3; MIM #204,200), also known as Spielmeyer–Vogt–Sjögren–Batten disease or shortly—Batten disease or juvenile neuronal ceroid lipofuscinosis (JNCL), is a rare lysosomal disorder inherited in an autosomal recessive trait." (PMID 36576693, 2023). "Recent investigations of other subforms of Batten disease (CLN1, CLN3, CLN6) have emphasized the influence of biological sex on disease and treatment outcomes; however, little is known about sex differences in the CLN8 subtype." (PMID 36369162, 2022). "Slower cell growth and altered development is consistent with other Batten disease models including CLN1 and CLN3 knockouts in yeast and premature ageing in a CLN3 knockout worm." (PMID 31100984, 2019).